DGAT2 (diacylglycerol O-acyltransferase 2)
Diseases named in the same sentence as DGAT2 in open-access papers (continued):
Sharing a sentence is not in itself a finding about the gene and the disease.
hepatoma (15 papers, 2016 to 2025). "DGAT2 has been reported to be associated with hepatocellular carcinoma malignancy by regulation of the cell cycle‐related gene expression." (PMID 32285560, 2020). "While MTP-dependent transfer of neutral lipids is dispensable for ApoE secretion, TG biosynthesis, redundantly catalyzed by DGAT1 and DGAT2, is required for efficient ApoE secretion in hepatoma cells." (PMID 40180213, 2025). "To study the influence of DGAT2 on the replication of HCV, we utilized the hepatoma cell line Lunet N hCD81 and generated stable cell lines overexpressing human DGAT2." (PMID 39241103, 2024). "It was proposed that overexpression of DGAT1 resulted in accumulation of small LDs around the cell periphery, whereas overexpression of DGAT2 contributed to increased large LDs intracellularly in rat hepatoma cells." (PMID 38500157, 2024). "In line with this, viral nucleocapsid protein has also been shown to induce DGAT1 and DGAT2 expression in the human hepatoma cell line Huh7, as evidenced by a reporter gene assay." (PMID 37113005, 2023). "For example, Dgat2 can affect the progression of hepatocellular carcinoma by regulating the cell cycle, and overexpression of Lpin1 can promote the proliferation and migration of ovarian cancer cells." (PMID 35122680, 2022). "Treatment of hepatoma cells with BMP2 induced DGAT2 expression and activity via intracellular SMAD signaling." (PMID 32561790, 2020). "Our in vitro studies revealed that the BMP-DGAT2 relationship is preserved across three distinct hepatoma cell lines, and DGAT2 is regulated via the canonical (SMAD-dependent) BMP signaling pathway." (PMID 32561790, 2020). "The direct exposure of hepatoma cells to LPS increased triglyceride-synthesizing Diglyceride acyltransferase 2, DGAT2 expression after 24 hours, and to FLG after 4 and 24 hours (p<0.05)." (PMID 27035341, 2016). "However, we found both ApoB and ApoE require nascent biosynthesis of TGs catalyzed by redundant activities of both DGAT1 and DGAT2 for their efficient expression and secretion by the hepatoma cells." (PMID 40180213, 2025). "However, in some other cancers, such as hepatocellular carcinoma 126 and melanoma 127, DGAT2 was identified to play a suppressive role." (PMID 36439875, 2022). "Interestingly, despite that the direct exposures also induced DGAT2 expression, fat accumulated in hepatoma cells only when the cells were challenged with media derived from FLG-treated adipocytes." (PMID 27035341, 2016). "To test the hypothesis that increased BMP signaling promotes DGAT2 expression in hepatoma cell lines other than HepG2, we investigated whether BMP signaling increased DGAT2 expression in HuH7 cells (a human hepatoma cell line), primary human hepatocytes, and AML12 mouse hepatocytes." (PMID 32561790, 2020). "Collectively, it can be inferred that DGAT1 and DGAT2 have different roles, and DGAT1 takes critical role of maintaining intracellular lipid homoeostasis in human hepatoma cells." (PMID 26493024, 2016). "Across this study, we identified HuH6 cells as a hepatoma cell line, in which DGAT2 overexpression does not hamper HCV replication, despite LD induction, suggesting slight differences in lipid metabolic pathways or rates between these cell systems." (PMID 39241103, 2024). "Hence, in Drosophila and rat hepatoma cells, many small or fewer large LDs accumulate respectively upon DGAT1 and DGAT2 overexpression." (PMID 39241103, 2024). "This latter observation was not seen in H4IIEC3 rat hepatoma cells when inhibiting TAG synthesis through siRNA silencing of DGAT1 and DGAT2." (PMID 30099850, 2018).
hypertriglyceridemia (12 papers, 2015 to 2024). A laboratory test result indicating elevated triglyceride concentration in the blood. "This trial demonstrated that the coadministration of ACC inhibitors with DGAT2 inhibitors can exert anti-MASH effects while resolving the hypertriglyceridemia associated with ACC inhibition." (PMID 39872142, 2024). "Hypertriglyceridemia can be induced by carbohydrates and DGAT2 was discussed to link glycaemia and triglyceridemia." (PMID 36746332, 2023). "Hypertriglyceridemia appears to be a feature of human DGAT1 deficiency and possibly is due to increased hepatic TG secretion mediated by DGAT2 and/or to impaired clearance of TG-rich lipoproteins." (PMID 28373485, 2017). "However, the co-administration of the DGAT2 inhibitor PF-06865571 effectively mitigated hypertriglyceridemia during a 6-week follow-up period." (PMID 39461620, 2024). "Our preliminary results demonstrate that metformin activates AMPK to reduce TG synthesis by inhibiting the XBP1-mediated DGAT2 pathway, at least in part, suggesting that XBP1 is a new metabolic mediator for metformin treatment of hypertriglyceridemia and associated metabolic disease." (PMID 36438823, 2022). "Our preliminary results demonstrate that metformin activates AMPK to reduce TG synthesis by inhibiting the XBP1-mediated DGAT2 pathway, at least in part, suggesting that XBP1 is a new metabolic mediator for metformin treatment of hypertriglyceridemia and associated metabolic diseases." (PMID 36438823, 2022). "A consideration may be that modulation of hepatic de novo lipogenesis via the SREBP-1c and DGAT-2 pathways by Jiangzhi Capsule is insufficient to improve fructose-induced hypertriglyceridemia." (PMID 26031670, 2015). "The present study aim to investigate the molecular mechanism by which metformin improves hypertriglyceridemia via regulation of diacylglycerol O-acyltransferase 2 (DGAT2) and X-box binding protein 1 (XBP1) in the liver and whether AMP-activated protein kinase (AMPK) is involved." (PMID 36438823, 2022). "Therefore, the present study investigated whether metformin improves hypertriglyceridemia via regulation of DGAT2 or XBP1 in the liver and whether AMPK is involved." (PMID 36438823, 2022). "Coadministration of the DGAT2 inhibitor PF-06865571 with the ACC inhibitor PF-05221304 reduced LFC and largely eliminated hypertriglyceridemia in a 6-week clinical trial follow-up period (NCT03776175 and NCT04321031)." (PMID 39872142, 2024). "Recently, an exciting result in phase II clinical trial shows that the co-administration of PF-0522134 (a new ACC1 inhibitor in clinical trial) and PF-6865571 (DGAT2 inhibitor) has a strong effect in treating NASH without the side effect of hypertriglyceridemia." (PMID 35359351, 2022).
breast carcinoma (10 papers, 2020 to 2025). "The peroxidation of excess FAs after inhibiting DGAT2 by PF-06424439 further increased the level of ROS and reactive nitrogen species induced by irradiation in breast cancer MCF-7 cells, causing more severe and unrepaired DNA damage." (PMID 38500157, 2024). "Consistently, inhibiting DGAT2 activity by a DGAT2 inhibitor (PF-06424439) effectively reduced the content of LDs and cell invasion ability in breast cancer MCF-7 cells, increased expression of E-cadherin, and suppressed expression of Vimentin and Snail." (PMID 38500157, 2024). "Treatments with inhibitors of DGAT1 (A922500, DGAT1i) and DGAT2 (PF-06424439, DGAT2i) activity for 48 h were able to counteract the increase of plasma membrane TGFβ-R1 and TGFβ-R2 levels in Elovl5-depleted breast cancer cells." (PMID 36056008, 2022). "In the present study, we report that DGAT2 inhibitor (PF-06424439) pre-treatment promoted radiosensitization of MCF7 breast cancer cells in vitro." (PMID 34576263, 2021). "One of the enzymes involved in lipid metabolism and LD production is DGAT2, which has been shown to be overexpressed in breast cancer cells." (PMID 34576263, 2021). "More surprisingly, both DGAT2 and CCDC69 have CNV mutations in Her2-positive breast cancer; DGAT2 expression increases as copy number increases, whereas an increase or increase in CCDC69 copy number results in a decrease in its expression." (PMID 32322168, 2020). "Diglyceride acyltransferase-2 (DGAT2) and coiled-coil domain-containing protein 69 (CCDC69) are two mRNAs that are lowly expressed in Her2-positive breast cancer and are involved in the risk scoring system." (PMID 32322168, 2020). "Interestingly DGAT2 is constitutively activated in various cancers including breast cancer (Hernández‐Corbacho & Obeid, 2019)." (PMID 36479627, 2022). "Therefore, DGAT2 appears as a new potential therapeutic target in the treatment of breast cancer (Hernández‐Corbacho & Obeid, 2019)." (PMID 36479627, 2022). "In this context, we evaluated the effect of PF-06424439, a selective DGAT2 inhibitor, on MCF7 breast cancer cells exposed to X-rays." (PMID 34576263, 2021). "In this work, we evaluated the effect of PF-06424439, a selective DGAT2 inhibitor, on MCF7 breast cancer cells exposed to X-rays." (PMID 34576263, 2021). "Similarly, inhibiting DGAT2 in cancer cells, like MCF-7 breast cancer cells, enhances their sensitivity to radiation." (PMID 40694426, 2025). "Likewise, a DGAT1 inhibitor (T-863 or PF-04620110) significantly decreased the total number of small and large LDs in breast cancer MCF-7 cells, suggesting that DGAT1 and DGAT2 interact in the process of LD formation in tumor cells." (PMID 38500157, 2024). "In our study, the expression of DGAT2 and CCDC69 in Her2-positive breast cancer was decreased and was closely related to patient prognosis; thus, they could be used as biomarkers to evaluate the condition of patients." (PMID 32322168, 2020).
diabetes (10 papers, 2019 to 2025). "Beyond skin diseases, DGAT2 is also implicated in systemic inflammatory diseases, like metabolic dysfunction–associated steatohepatitis (MASH), diabetes, and atherosclerosis." (PMID 40694426, 2025). "Increased DGAT2 expression was present not only in nerves assessed in murine models of type 2 diabetes but also in sural nerve biopsies from hyperlipidaemic individuals with diabetes and peripheral neuropathy." (PMID 33084971, 2021). "Furthermore, TDQ reversed diabetes-induced decrease in the mRNA and protein expression of PPARγ and elevation in the mRNA and protein levels of DGAT2 in the liver." (PMID 31019978, 2019). "DGAT2 was identified as a key upregulated enzyme in HFD and HFD-STZ mice, which was also the case in sural nerve biopsy from hyperlipidaemic diabetes patients with PN." (PMID 31822493, 2020).
gastric cancer (8 papers, 2021 to 2025). A primary or metastatic malignant neoplasm involving the stomach. "In gastric cancer cells, treatment with FAs or adipocytes induced intracellular LD formation through transcriptional upregulation of DGAT2 in a C/EBPα-dependent manner." (PMID 38786008, 2024). "Specifically, mice fed a high-fat diet showed overexpression of diaglycerol acyl transferase 2 (DGAT2); when those mice were implanted with gastric cancer cells, the overexpression of DGAT2 led to increased peritoneal metastasis." (PMID 37205182, 2023). "When DGAT2 was inhibited in vivo, it synergized with chemotherapeutic drugs to significantly inhibit peritoneal metastasis of gastric cancer." (PMID 35785165, 2022). "A study focusing on gastric cancer revealed increased expression of DGAT2 in cancer cells cocultured with adipocytes." (PMID 36439875, 2022). "DGAT2 is critical for tumor metastasis and progression in gastric cancer." (PMID 40426878, 2025). "Five genes, e.g., DGAT2, JAKMIP1, KRT7, PGLYRP1, and TINAGL1, showed very low correlation coefficient and/or insignificant p-values, suggesting they might not be regulated by KLF5 in human gastric cancer." (PMID 33923166, 2021).
hyperlipidemia (8 papers, 2020 to 2025). "Diacylglycerol O-acyltransferase 2 (DGAT2) inhibitors are promising ones aimed at the treatment of metabolic disorders, particularly non-alcoholic steatohepatitis, type 2 diabetes, and hyperlipidemia." (PMID 38919858, 2024). "Interestingly, we found that ACC1 and FAS were increased by STZ treatment, while DGAT2 was upregulated in HFD-treated mice, indicating that hyperglycemia and hyperlipidemia might promote lipogenesis by activating distinct lipogenic genes, respectively." (PMID 33186123, 2020).
type 2 diabetes (7 papers, 2019 to 2025). "All malignancies, nonalcoholic fatty liver disease (NAFLD), and type 2 diabetes have been linked to abnormal Dgat2 expression." (PMID 40510478, 2025). "We suggest that this ability of TDQ to provide multifaceted actions in the IR of type 2 diabetes can be attributed to its biological actions associated with PPARγ activation and DGAT2 inhibition." (PMID 31019978, 2019). "It demonstrates that TDQ treatment, associated with increased hepatic PPARγ and reduced DGAT2 expression, targets multiple risk factors of the type 2 diabetes; additionally, it is a glucose- and lipid-lowering agent with a strong ability to treat diabetic complications." (PMID 31019978, 2019). "The present study hypothesizes that TDQ, acting as a PPARγ agonist and a DGAT2 inhibitor, not only alleviate glucose and lipid metabolism disorder but also ameliorate IR in type 2 diabetic rats." (PMID 31019978, 2019). "The results of liquid chromatography/electrospray ionization/tandem mass spectrometry revealed that high FTO expression in type 2 diabetes mellitus (T2DM) patients accompanied by increased mRNA expression levels of key genes of glucose metabolism (FOXO1, G6PC, and DGAT2)." (PMID 36830642, 2023).
dyslipidemia (5 papers, 2018 to 2025). "Inhibition of either DGAT1 or DGAT2 has been considered to be an attractive target for the treatment of dyslipidemia." (PMID 30333041, 2018). "Additionally, DGAT2 promotes the development of dyslipidemia and NAFLD." (PMID 37660122, 2023).
glioblastoma (5 papers, 2020 to 2025). The most malignant astrocytic tumor (WHO grade IV). "While DGAT1 inhibition suppresses tumor growth in various cancers, including glioblastoma, melanoma, and prostate cancer, overexpression of DGAT2 inhibits cell proliferation in hepatocellular carcinoma (HCC)." (PMID 41041279, 2025). "The expression of DGAT1 in the glioblastoma tumor is much higher than that of DGAT2." (PMID 37046844, 2023). "Moreover, an even higher dose of A922500 (47 μM) was unable to suppress LD dependent on DGAT2 or to markedly suppress viability in glioblastoma cells over-expressing DGAT2, consistent with A922500 being a selective DGAT1 inhibitor at this concentration." (PMID 35732120, 2022). "Third, IL18 upregulated genes consistent with an effector phenotype that supports growth and proliferation, such as genes related to fatty acid biosynthesis (Dgat2, Scd2, Hacd3) and Hif1a, which promotes glycolysis as well as migration of Tregs in glioblastoma." (PMID 32687059, 2020). "The expression of DGAT1 in glioblastomas (GBM) tissues was significantly higher than that of DGAT2, and the expression of DGAT1 in poorly differentiated tumor tissues was higher than that in well-differentiated tumor tissues." (PMID 38500157, 2024). "DGAT2, a functionally related albeit structurally distinct enzyme, appeared less important than DGAT1 for melanoma LD formation, cell growth, and survival, as was shown previously to be the case for glioblastoma cells." (PMID 35732120, 2022). "Furthermore, higher expression of DGAT1 in glioblastoma may be associated with worse prognosis for glioblastoma patients, although GEPIA does not associate the expression of DGAT1 or DGAT2 with prognosis in glioblastoma patients." (PMID 37046844, 2023).
liver fibrosis (5 papers, 2015 to 2025). "In MASH, DGAT2 is an important therapeutic target, as its inhibition can reduce liver fibrosis but may also cause developmental toxicity during pregnancy in rodents." (PMID 40694426, 2025). "DGAT2 inhibitors and ACC inhibitors can reduce liver fibrosis." (PMID 39232826, 2024).
non-alcoholic fatty liver disease (4 papers, 2012 to 2024). "So far, DGAT2 inhibition has not been attempted in a clinical setting but was reported as a well-tolerated therapeutic option for patients with nonalcoholic fatty liver disease." (PMID 37644753, 2023). "In a recent trial of non-alcoholic fatty liver disease (NAFLD), acetyl-coenzyme A carboxylase (ACC) inhibitor was used alone or cooperated with a diacylglycerol acyltransferase 2 (DGAT2) inhibitor in patients to observe the change of magnetic resonance imaging - proton density fat fraction in liver." (PMID 35911719, 2022).
non-alcoholic steatohepatitis (4 papers, 2021 to 2024). "Early-phase clinical trials inhibiting DGAT2 decreased liver fat content in patients, suggesting that DGAT2 may be effective in preventing metabolic dysfunction-associated steatohepatitis (formally known as non-alcoholic steatohepatitis)." (PMID 39872855, 2023).
colon cancer (3 papers, 2021 to 2023). "The qPCR data showed here that DGAT1 mRNA was the major form and the two variants of DGAT2 mRNA accounted for only half of the DGAT1 mRNA levels in the human colon cancer cells." (PMID 33723275, 2021). "In contrast to mouse macrophages, we showed here that gossypol inhibited DGAT1 and DGAT2 expression in the human colon cancer cells." (PMID 33723275, 2021). "DGAT2 mRNA is the major DGAT mRNA in mouse adipocytes and macrophages, but DGAT1 mRNA was the major form in the human colon cancer cells." (PMID 37705049, 2023). "DGATs are classified with DGAT1 and DGAT2 subfamilies in animals and additional DGAT3 subfamily in plants with DGAT2 mRNA being the major form of DGAT mRNAs in mouse adipocytes and macrophages but DGAT1 as the major one in the colon cancer cells." (PMID 35058516, 2022).
Hyperinsulinemia (3 papers, 2012 to 2020). An increased concentration of insulin in the blood. "In this study, Evo also reduced lipogenesis by suppressing the Dgat2 mRNA level and improved hyperinsulinemia and liver enzymes." (PMID 32937958, 2020). "RGS5 deficiency would likely involve enhanced Gαi-mediated signal pathway and be in charge of increased lipogenesis (mediated by DGAT1, DGAT2 and GPAT1) and decreased lipolysis (mediated by HSL and ATGL), under the conditions of hyperinsulinemia and high FFA, which can induce adipocyte hypertrophy." (PMID 22272317, 2012).
melanoma (3 papers, 2022 to 2025). A malignant, usually aggressive tumor composed of atypical, neoplastic melanocytes. "Conversely, DGAT2 may function as a tumor suppressor in certain cancer types, such as HCC and melanoma." (PMID 40694426, 2025). "Furthermore, we confirmed elevated expression of human DGAT1 but not DGAT2 mRNA in melanoma tumors relative to both skin and nevi and elevated DGAT1 protein in human melanoma cell lines relative to primary melanocytes irrespective of NRAS or BRAF mutational status." (PMID 35732120, 2022).
atherosclerosis (2 papers, 2024 to 2025). A disease characterized by the build-up of fatty material and calcium deposition in the arterial wall resulting in partial or complete occlusion of the arterial lumen. "This review focuses on the role and mechanism of action of miR-26 in atherosclerosis, including the detection value of miR-26 and the potential development of drugs targeting its downstream genes, such as ACC1/2, COL1A1, CPT1A, FBP1, DGAT2, and SMAD7, to provide insight for drug development." (PMID 38195542, 2024).
Cachexia (2 papers, 2014 to 2020). Severe weight loss, wasting of muscle, loss of appetite, and general debility related to a chronic disease. "We observed reduced amplitudes in the mRNA expression of Reverbα Per2, Pparγ C/ebpα, and associated genes (Fas, Lpl, Scd1, Dgat2) and a parallel increase in Bmal1, Cry1, Pbe and Tfam indicating alterations in the core clock regulation and lipid homeostasis during cachexia." (PMID 24667661, 2014). "Also, expression of PEPCK, DGAT2, and FABP1 tended to be up‐regulated in cachexia." (PMID 33084249, 2020).